VIM (vimentin)
Diseases named in the same sentence as VIM in open-access papers (continued):
Sharing a sentence is not in itself a finding about the gene and the disease.
glioma (continued). "The up-regulation of E-cadherin level and the down-regulation of vimentin were observed in U251 cells after β-asarone treatment, suggesting β-asarone may block the process of EMT in glioma cells." (PMID 29547514, 2018). "Moreover, NUCL, TRIM28, VIM, and NAP1L1 were indicated as good markers to distinguish glioma tissues from reference tissues." (PMID 28498803, 2017). "Although siRNA knockdown of HIF1/2α reduced glioma cell migration to levels seen under normoxia, the remaining migratory cells did not express the mesenchymal marker vimentin." (PMID 25957416, 2015). "Protein analysis of tumors from animals fed the KD showed reduced expression of both pro- and activated-MMP-2, and the mesenchymal marker, vimentin, which is upregulated in the epithelial-to-mesenchymal transition (EMT) that occurs within invasive glioma cells." (PMID 26083629, 2015). "For this analysis we treated A172 glioma cells and the HF2354 GSCs with IL-6 and found that this treatment upregulated the expression of the mesenchymal markers vimentin and FN in these cells, increased cell migration of the A172 cells and of the GSCs, HF2354 and HF2359." (PMID 26267319, 2015). "Moreover, silencing of IL-6 downregulated the expression of the mesenchymal marker vimentin in the HF2355 and HF2490 GSCs and inhibited cell migration of U87 glioma cells and of the HF2490 and HF2303 GSCs." (PMID 26267319, 2015). "The glioma stem cells obtained from CD133+ cells demonstrated increased expression of Twist1 and Sox2 accompanied by significant increase in the mesenchymal markers such as N-cadherin, vimentin and β-catenin." (PMID 22184289, 2011). "Menin is also highly expressed in the cytoplasm of glioma cells, where it interacts with the type III intermediate filament proteins glial fibrillary acidic protein (GFAP) and vimentin, suggesting that menin may also promote migration and metastasis of glioma cells." (PMID 39336822, 2024). "VIM (Vimentin) is highly expressed in gliomas compared to non-tumor tissues." (PMID 38418476, 2024). "To verify if c-Jun binds to the VIM gene promoter, we performed an electrophoretic mobility shift assay (EMSA) using nuclear extracts from normal human astrocytes (NHA) as a control, GII glioma-derived cell cultures (WG12) and two human established cell lines derived from GIV (LN18, LN229)." (PMID 36850002, 2023). "Here, we demonstrated that E-cadherin was significantly augmented while N-cadherin, vimentin, and p-FAK/FAK ratio was reduced in glioma cells with MEOX2 knockdown, and the expression of these molecules showed the opposite trend in MEOX2 overexpression glioma cells." (PMID 35436995, 2022). "To explore whether the relationship between ACOT12 and EMT is also involved in the progression of glioma, we validated the effect of modulating ACOT12 expression on the expression levels of TWIST2 and other EMT markers, including vimentin and N-cadherin, by RT-qPCR and western blotting." (PMID 35986010, 2022). "Furthermore, the effects of MEX3A on glioma cell migration could be partially explained by the downregulated expression of EMT-related proteins, including N-cadherin, Snail, and Vimentin." (PMID 33414423, 2021). "Further, IDH1mt gliomas, irrespective of grade, showed greater spatial heterogeneity but lower molecular heterogeneity of biomarkers associated with angiogenesis (VEGR2, CD31, SMA, S100A4) and invasion (n-cadherin, cofilin, collagen IV, GFAP and vimentin)." (PMID 31881020, 2019). "Notably, GFAP expression is absent and vimentin expression is variable in C6 glioma cells." (PMID 33790744, 2021).
glioma (continued). "U87 and U251 glioma cells upon pcDNA3.1‐SFRP1 treatment was found to have elevated SFRP1 and E‐cadherin expression and reduced p‐GSK‐3β, β‐catenin, N‐cadherin, Vimentin, and Snail expression, with no change in GSK‐3β expression." (PMID 36756719, 2023). "An increased invasion capability, associated with a reduced VEGF/VEGFR2 expression and increased vimentin and CD44 epithelial-mesenchymal transition markers in siTRPML2, but not in enforced-TRPML2 or ML2-SA1-stimulated glioma cells, was demonstrated." (PMID 35054871, 2022). "We found that the glioma tissue was diffusively positive for GFAP, Nestin, slightly positive for Olig2, S-100; the positive rate of Ki-67 was 65% and negative for Vimentin." (PMID 33391433, 2021). "Moreover, most EMT biomarkers, including N-cadherin, snail, slug, vimentin, TWIST1, and TWIST2, were significantly correlated with BDKRB2, which suggested that BDKRB2 might profoundly interact with these key molecules of EMT, further confirming the involvement of BDKRB2 in glioma EMT." (PMID 33686021, 2021). "The expression of ZEB1 and vimentin as well as Ki-67 (MKI67) as proliferation marker, was increased in co-cultured glioma cells as compared to glioma cells cultured without LAD2 cells." (PMID 28445977, 2017). "Our study result demonstrated that PLOD3 silencing inhibits glioma cell migration that could be categorized as type 3 EMT due to suppressing Snail and Twist expression, but no change of Vimentin." (PMID 29644003, 2018).
pancreatic cancer (213 papers, 2006 to 2026). "Transcript expression levels of CDH1 and VIM were also analyzed according to the aggressiveness and invasiveness grade of tumors to ascertain associations with such pancreatic cancer features." (PMID 40305202, 2025). "The untreated murine PDAC tumor organoid showed substantial CK19 staining, representing the epithelial pancreatic tumor cells, and vimentin staining, representing the cancer-associated fibroblasts." (PMID 40563856, 2025). "Overall, our findings suggest that DDX3X promotes migration and invasion through EMT in vitro and that the expression of DDX3X is closely linked to vimentin-mediated progression in pancreatic cancer." (PMID 38316768, 2024). "As for its roles in EMT, a publication has demonstrated that depletion of endogenous TUFT1 impacts the expression levels of EMT-associated proteins (E-cadherin and Vimentin) in pancreatic cancer." (PMID 36797791, 2023). "In our study, the significant association of vimentin-positive CTCs with prognosis highlights the potential importance of mesenchymal-type CTCs in pancreatic cancer management." (PMID 37736542, 2023). "Analogous results were obtained in pancreatic tumor cells where the expression of Src was linked to decreased E-cadherin and elevated vimentin levels." (PMID 36547158, 2022). "While N-cadherin and vimentin are usually expressed at low level in epithelial cells, their aberrant expression is a very well-known phenomenon in breast, prostate, and pancreatic cancer cells, causing increased aggressiveness and metastasis." (PMID 37529796, 2022). "Epithelial marker like E‐cadherin was decreased, whereas mesenchymal markers, including Snail, Twist, vimentin and N‐cadherin, were increased in high‐risk group from hepatic–biliary–pancreatic tumors." (PMID 36054420, 2022). "In the current study we evaluated the biological activities of a novel vimentin-targeting small molecule compound (R491) in cell lines of human lung, brain, gastric, liver, and pancreatic cancers, and investigated their underlying mechanisms." (PMID 34305581, 2021). "Western blot analysis of the expression of EMT-associated proteins and HIF-1α/SDF-1/CXCR4 of pancreatic cancer tissues revealed that bufalin significantly downregulated vimentin but upregulated E-cadherin in PANC-1 cells." (PMID 32362830, 2020). "In a variety of pancreatic cancer cell lines, extracellular stiffness is associated with elevated expression of vimentin, reduced expression of E-cadherin, and nuclear localization of β-catenin, YAP and TAZ, changes known to be linked to EMT." (PMID 29903049, 2018). "Assessment of the utility of vimentin autoantibodies as diagnostic markers in pancreatic cancer also needs to be addressed in further studies." (PMID 18769604, 2006). "CDH1 and VIM transcript expression were analyzed by qPCR, according to different variables to ascertain associations with patients’ specific features and predisposition to develop pancreatic cancer." (PMID 40305202, 2025). "In addition, loss of CK7 and trypsin expression in pancreatic cancer cells spheres suggest both morphological and functional de-differentiation, while the expression of Vimentin suggests their mesenchymal phenotype." (PMID 36497278, 2022). "Many studies have shown VIM to be substantially expressed in liver metastases of pancreatic tumours, and expression is associated with increased invasiveness and metastasis potential for epithelial breast carcinoma, hepatocellular carcinoma and cervical carcinoma." (PMID 19216797, 2009). "Although our cases were not selected with regard to their postoperative course, it is possible that the association between tumour epithelial vimentin expression and outcome of pancreatic cancer could be influenced by differences in postoperative chemoradiotherapy." (PMID 21448168, 2011). "In this study, we demonstrate that the chromatin regulator PBRM1 binds to the vimentin promoter region and epigenetically regulates its expression in pancreatic cancer." (PMID 40454484, 2025).
pancreatic cancer (continued). "Overall, NSYSU-115 effectively reduces vimentin expression in pancreatic cancer cells at higher doses." (PMID 40762406, 2025). "The inhibition of EMT markers like E-cadherin, vimentin, and N-cadherin by curcumin contributes to its anti-cancer effects and the sensitization of radioresistance in Panc-1 pancreatic cancer cells." (PMID 41465451, 2025). "A previous study reported that NR5A2 knockdown in pancreatic cancer led to an increase in the expression level of E‐cadherin and a decrease in the expression levels of snail and vimentin, suggesting that NR5A2 is involved in the EMT process." (PMID 38358044, 2024). "Our results showed that up-regulation of MSLN was accompanied with the expression changes of E-Cadherin, Vimentin and Snail in pancreatic cancer cells, hence promoting EMT." (PMID 38628720, 2024). "Immunofluorescence staining for N-cad and VIM showed that GEM reduced the migratory capacity of pancreatic cancer cells, with a more pronounced effect observed in combination with IEVs-PFD/138." (PMID 38910148, 2024). "It was further verified that NDUFS2 promoted pancreatic cancer cell migration by regulating the expression of E-cadherin and vimentin." (PMID 38653740, 2024). "In vitro analysis revealed that PDAC-X1 cells exhibited epithelial morphology and cell markers (CK7 and CK19), expressed cancer-associated markers (E-cadherin, Vimentin, Ki-67, CEA, CA19-9), and produced pancreatic cancer-like organs in suspension culture." (PMID 38965506, 2024). "We also observed decreased fibroblast activation markers such as vimentin, αSMA, and ColIV, suggesting JM modulated the stromal compartment of pancreatic cancer." (PMID 38139993, 2023). "qPCR was used to verify that AREG was knocked down in pancreatic cancer cell lines and that the expression of E-cadherin was upregulated and vimentin was decreased in AREG siRNA-transfected cells." (PMID 37604948, 2023). "Studies have shown that vimentin antibodies are more effective for isolating CTCs from certain cancers, such as breast and pancreatic cancer, than EpCAM antibodies alone." (PMID 37345161, 2023). "Studies carried out on patients with pancreatic cancer have shown poor survival in the presence of vimentin." (PMID 37371811, 2023). "For example, BACH1 inhibits EMT by decreasing vimentin expression in pancreatic cancer but promotes EMT by increasing vimentin expression in esophageal cancer." (PMID 37228820, 2023). "EMT is also associated with tumor budding, which accounts for gemcitabine resistance; a study indicated that tumor budding with vimentin expression becomes a key process in pancreatic cancer and is responsible for progression and gemcitabine resistance." (PMID 36831572, 2023). "In this paper, we evaluated the efficacy of isolating CTCs from the blood of patients with prostate and pancreatic cancer using EpCAM (an epithelial marker) and vimentin (a mesenchymal marker) antibodies individually and in combination." (PMID 37345161, 2023). "The downregulation of β-catenin, Vimentin and Snail and the upregulation of E-cadherin were observed as a result of Gpx-2 silencing in pancreatic cancer cells." (PMID 37834097, 2023). "Differently, Vimentin was localized in most pancreatic cancer cells but only in a small number of adherent epithelial ones, while it was absent in cell spheres." (PMID 36497278, 2022). "The inhibition of NF-κB can reduce the expression of VIM and affect the epithelial mesenchymal transformation and nerve infiltration in pancreatic cancer." (PMID 35962388, 2022). "Activation of AMPK/mTOR signalling by irisin was also found to inhibit EMT by increasing E‐cad expression and decreasing vimentin expression in pancreatic cancer." (PMID 36251949, 2022). "We also found that compared with the sh mTOR group, activating the HGF/c-Met signaling pathway recovered the N-cadherin and Vimentin expression of pancreatic cancer cells but decreased the E-cadherin expression in the HGF + sh mTOR group." (PMID 35449152, 2022).
pancreatic cancer (continued). "It is reported that hnRNPA2B1 is highly expressed in pancreatic cancer and is related to higher expression of N-cadherin and vimentin, as well as lower expression of E-cadherin." (PMID 36051357, 2022). "Some pancreatic cancer cell lines endogenously express Vimentin, especially our target cell lines MIA PaCa-2 and PANC-1, cell lines with an epithelial-mesenchymal phenotype." (PMID 33526844, 2022). "Estimation of exosomal vimentin levels after gemcitabine treatment provides prognostic information for individuals with pancreatic cancer." (PMID 35664698, 2022). "The PANC-1 cells used in the present study exhibit several mesenchymal characteristics among several pancreatic cancer cell lines, with low levels of E-cadherin and high levels of vimentin expression." (PMID 34885065, 2021). "The gene expression analysis of EMT markers Zeb1, Vimentin, and Col1a1 were significantly decreased in YFP sorted primary pancreatic cancer cell lines from KPC;ST mice, along with complete loss of Snai1 and Twist1." (PMID 33852841, 2021). "Correspondingly, analysis of western blot showed that miR-181a inhibited the expression of adhesion proteins such as N-cadherin, E-cadherin, Vimentin and Snail-1 in pancreatic cancer cells." (PMID 34374662, 2021). "In the presence of isolated effector CD4+ T cells, pancreatic cancer cells show upregulation of VIM, L1CAM and ZEB1, combined with a more migratory phenotype, which was reverted by blocking IL6 and TNFα." (PMID 34459003, 2021). "Overexpression of miR-509-5p increases the sensitivity to gemcitabine in pancreatic cancer by targeting vimentin." (PMID 33579377, 2021). "Our study found that cytoskeletal protein remodeling mediated by TGF-β1 and vimentin affected the balance of cell adhesion and dissociation in human colorectal, lung, and pancreatic cancer cell lines." (PMID 34830801, 2021). "In this study, Snail and mesenchymal proteins such as N-cadherin, Vimentin were decreased, while E-cadherin was increased after CP treatment, which indicated that CP inhibited pancreatic cancer metastasis by inhibiting the EMT." (PMID 34068565, 2021). "Since markers such as integrin β-1 or vimentin play an essential role in adhesion and invasiveness of pancreatic carcinoma cells, we analysed the relationship between light-induced TLR4 activation and integrin β-1 and vimentin expression." (PMID 34502140, 2021). "Vimentin has been shown to increase pancreatic cancer cell invasion, while silencing vimentin cells reduces invasiveness." (PMID 32670437, 2020). "Warfarin treatment also decreased vimentin expression in pancreatic cancer cells, suggesting that warfarin also acts on the cancer cells altering their plasticity." (PMID 32174917, 2020). "In pancreas cancer cells, 9 induced Par-4 leading to the suppression of vimentin, Twist-1, and Sox2." (PMID 35582221, 2020). "To further investigate the effect of anti-Gas6 on vimentin expression in pancreatic cancer cells in our in vivo tumor model, we analyzed vimentin protein expression in pancreatic tumor tissues from control and anti-Gas6 treated mice." (PMID 32174917, 2020). "Both the mesenchymal marker vimentin and the epithelial marker EpCAM are known to be overexpressed in most pancreatic carcinomas." (PMID 31963309, 2020). "Evidence in support of the fact that B7-H4 influences migration-related proteins including E-cadherin and vimentin and then enhances the migratory and invasive potential of pancreatic cancer has been increasing." (PMID 31619714, 2019). "Here we analyzed if the intermediate filament protein Vimentin (encoded by VIM), a marker for EMT associated with pancreatic tumor budding, is also targeted for inhibition by RAC1B." (PMID 31817229, 2019). "In fact, EMT strongly correlates with the systemic aggressiveness of pancreatic tumors and is associated with tumor budding as inferred from association with the EMT marker Vimentin." (PMID 31817229, 2019).